INS (insulin)
Diseases named in the same sentence as INS in open-access papers (continued):
Sharing a sentence is not in itself a finding about the gene and the disease.
diabetes (continued). "We conducted a secondary analysis of population-based data from 58,128 aged 18–85 yrs from Scottish Health Surveys (2003, 2008–2011) and Health Surveys for England (2003–2006, 2008–2013), excluding pregnant women and insulin-treated diabetes." (PMID 30927105, 2019). "Children born with type 1 diabetes mellitus, in which the body cannot produce insulin, require life-long insulin therapy." (PMID 30256722, 2019). "Other drugs included insulin used for diabetes, vanadium + aonys in the clinical trial for type 2 diabetes, and alimentary/metabolic disease, targeting INS and SLC2A4, respectively." (PMID 31699147, 2019). "At the end of this study (5 weeks after the onset of induction of diabetes), the diabetic rats had higher water intake, food consumption, plasma glucose, and plasma triglycerides and lower body weight and plasma insulin than control rats." (PMID 31583053, 2019). "The second class of diabetes, type 2, is characterised by a chronic hyperglycemia resulting from defects in insulin action, which leads to a reduction of insulin sensitivity and insulin resistance." (PMID 32232085, 2018). "Following the utilization of PPARγ agonists for type 2 diabetes mellitus in improving insulin sensitivity, the pleiotropic effects of PPARγ in neurodegenerative diseases like AD have been increasingly investigated in recent years." (PMID 30420872, 2018). "The role of PTPs in insulin signaling pathways and diabetes has previously been studied using vanadium compounds, which are able to reduce serum glucose levels in both type 1 and type 2 diabetic animal models." (PMID 30558294, 2018). "New basal-bolus protocols with appropriate adjustments of short acting insulin are needed to treat patients with diabetes on glucocorticoid therapy." (PMID 30373567, 2018). "The heart responds to insulin, and insulin resistance is a prominent defect in individuals who suffer from diabetes, obesity, and metabolic syndrome." (PMID 29484207, 2018). "Of these isoforms, it is the disruption of Akt2 that is associated with impaired glucose uptake, insulin resistance and diabetes in humans and mice, indicating that Akt2 is particularly important in mediating metabolic insulin responses." (PMID 30524379, 2018). "Considering the close association of islet beta cellfailure in obesity-associated diabetes,it is reasonable to predict the involvement of MAFB in DM development because of thebeta cell compensation for insulin resistance." (PMID 29846411, 2018). "Rebolledo and Arellano comment that the usage rate of oral diabetes medications among adults with type 2 diabetes has remained almost three times higher than that of insulin (50.3 versus 17.8%)." (PMID 30116737, 2018). "It is known that one of the earliest detectable abnormalities in the development of diabetes is the deterioration of the early insulin response after glucose loading, and the aggravation of insulin sensitivity affects the development of diabetes." (PMID 30478026, 2018). "Increasing numbers of patients with type 2 diabetes mellitus are progressing to insulin therapy, and despite its potency many such individuals still have suboptimal glycaemic control." (PMID 29788908, 2018). "Further study is needed to assess the impact of optimized insulin dosing on other diabetes-related health care costs in a usual practice setting." (PMID 32685571, 2018). "As expected, insulin sensitivity was improved significantly in the diabetes + KD and diabetes + KD + AE groups, compared with the diabetes group, as shown by GTT and ITT." (PMID 29743883, 2018). "A model was derived based on an individual’s observed HbA1c measures from the first eligible HbA1c after the diagnosis of diabetes through to the study end (defined as insulin initiation, death, leaving the area or end of follow-up)." (PMID 29260253, 2018).
diabetes (continued). "The UK Prospective Diabetes Study (UKPDS) reported that the presence of positive GAD antibody (GADA) concentrations predicted an increased likelihood of requirement for insulin." (PMID 29260253, 2018). "This included individuals who questioned their ability to take part in activities or eat certain foods, and being unsupportive when they performed diabetes‐related tasks, such as checking blood glucose and administering insulin." (PMID 29961962, 2018). "It has been extensively studied the delay of the period to insulin introduction in type 2 diabetes mellitus (T2DM) patients." (PMID 30386438, 2018). "We identified key genes (GYS1, PYGL, and PSAT1) from both pathways that have previously been demonstrated to play a role in glucose tolerance/ insulin sensitivity in models of obesity and diabetes and epidemiological studies." (PMID 30483256, 2018). "D. melanogaster insulin signaling has been evolutionarily conserved, and both types 1 and 2 diabetes can be modeled." (PMID 29854726, 2018). "People with type 1 diabetes mellitus (T1DM) are unable to produce insulin due toautoimmune destruction of their insulin-secreting beta cells." (PMID 29627802, 2018). "Type 1 Diabetes (T1D), previously known as Insulin-Dependent Diabetes Mellitus (IDDM), is an autoimmune disease resulting from the deficiency of insulin." (PMID 29589561, 2018). "A form of diabetes known as type 1 diabetes, where the body stops making insulin, usually starts in childhood and can sometimes appear during the first six months of life." (PMID 30412050, 2018). "A potential indicator of worse prognosis was age (HR = 1.144), creatinine concentration (HR = 1.007), and diabetes (HR = 2.063) especially diabetes requiring insulin therapy (HR = 3.966)." (PMID 28396904, 2018). "In this study, we observed that amount of pancreatic beta-cells, weight of the pancreas, and insulin level in pancreas were reduced in diabetes mice." (PMID 29853958, 2018). "EVs released by macrophages of adipose tissue can modulate liver and muscle glucose and insulin metabolism, favoring diabetes." (PMID 29808089, 2018). "Folate supplementation decreases glycosylated haemoglobin, fasting blood glucose, insulin and homocysteine in type 2 diabetes mellitus patients." (PMID 29464546, 2018). "Administration of insulin is largely painless, and the level of patient compliance is not different from compliance with other medications used to treat diabetes or other medical conditions such as hypertension." (PMID 29682315, 2018). "In the case of beta cells this leads to impaired insulin secretion and cell death which both play key roles in the regulation of the diabetes." (PMID 30004412, 2018). "Diabetes is characterized by high blood glucose, either because the body cannot produce enough insulin or is unable to use it effectively, consequently leading to insulin resistance or deficiency." (PMID 30564194, 2018). "Skeletal muscle is the primary site of insulin resistance in obesity and type 2 diabetes mellitus since it displays the highest level of insulin-stimulated glucose utilization." (PMID 29558390, 2018). "Type 2 diabetes mellitus (T2DM) is a progressive metabolic disorder characterized by abnormal insulin secretion and utilization." (PMID 29527102, 2018). "Diabetes (DM) is characterized by a resistance to insulin (type II) or the inability to produce insulin (type 1) and associated with end organ damage and life-threatening complications." (PMID 29546642, 2018). "The average duration of diabetes was 7.1 years (SD 5.5), with 26% of members having hemoglobin A1c > 8.0% and 21% receiving insulin." (PMID 29625571, 2018). "We aim to evaluate the effectiveness of diabetes self-management education via a smartphone app in T2DM patients on insulin therapy." (PMID 30348142, 2018).
diabetes (continued). "Diabetes mellitus (DM) is a complex metabolic disease characterized by hyperglycemia resulting from defects in insulin secretion and/or action; and type 1 diabetes mellitus (T1DM) and type 2 diabetes mellitus (T2DM) are its major forms." (PMID 30258406, 2018). "Performing continuous glucose monitoring led to early intervention with insulin therapy (0,25 U/kg of long acting insulin) following diagnosis of significant glucose intolerance or early diabetes." (PMID 29799376, 2018). "Pig insulin was used for decades to treat diabetes until recombinant human insulin became available." (PMID 29609635, 2018). "The Multicenter 2 × 2 Factorial Randomized Controlled Trial Comparing Insulin Pump with Multiple Daily Injections and Continuous with Conventional Glucose Self-monitoring (HypoCOMPaSS) was one of the largest RCTs of diabetes technologies in those with IAH." (PMID 29423581, 2018). "Insulin sensitivity is thought to be involved in the pathophysiology of both type 1 and type 2 diabetes mellitus and insulin, and related signaling pathways are also key mediators of embryogenesis and early development." (PMID 30693064, 2018). "T1DM results from the autoimmune destruction of the insulin-producing β cells of Langerhans islets; it is usually diagnosed in children and young adults and represents less than 10% of all cases of diabetes." (PMID 29541644, 2018). "The results of this study demonstrate that multiple markers including insulin, leptin/adiponectin, and 10- and 12-Z,E-HODE/LA can be used to detect diabetes risk at an early stage." (PMID 29610560, 2018). "On the other hand, although high values of FLI are associated with reduced insulin sensitivity, fatty liver diagnosed as FLI ≥60 has been shown to be a predictor of incident diabetes independently of insulin resistance." (PMID 29856820, 2018). "T1D patients need daily administration of insulin and are likely to suffer ketoacidosis, coma and death." (PMID 30294283, 2018). "The CCN5 KO mice also exhibited mild diabetes characterized by high fasting glucose levels and impaired insulin and glucose tolerances." (PMID 30485307, 2018). "The aim of this study was to determine the level of awareness of hypoglycemia, the level of fear for hypoglycemia, and the response to hypoglycemic events among insulin-treated diabetes patients from Central and Eastern Europe (CEE)." (PMID 29524189, 2018). "Despite intensive insulin therapy, target hemoglobin A1c (HbA1c) levels remain above 7.0% in many patients with type 1 diabetes mellitus (DM) with poor metabolic control." (PMID 29338714, 2018). "The first trait/PC is aligned to traditional complications seen with long term diabetes such as insulin use, retinopathy, duration of diabetes, and peripheral vascular disease, with ethnicity also being one of the major variables in this domain." (PMID 29311660, 2018). "In contrast, 11.2% of the untreated diabetic animals died within 4 days after confirmation of diabetes, and 33.3% of those treated once daily with insulin died within 7 days." (PMID 30333575, 2018). "We further compared insulin regimen between CHI patients with diabetes and T1DM patients at diabetes onset and at follow-up, i.e. the proportion of patients treated with CT, ICT and CSII." (PMID 30577875, 2018). "The percentages of patients with DME (not clinically significant) were higher in patients less than 60 years, male, had diabetes for more than 10 years, taking insulin, and with higher A1c or poor glycemic control." (PMID 29924846, 2018). "There are many theories to explain the connection between diabetes and psychiatric disorders, including abnormal glucose metabolism, impaired brain insulin signaling, neurogenesis, and alterations in glucocorticoid levels." (PMID 30622594, 2018). "APN has anti-atherogenic and anti-inflammatory properties and increases insulin sensitivity, along with playing a protective role against AS and diabetes." (PMID 29440225, 2018).
diabetes (continued). "In this study, we assessed prediabetes and diabetes by 75 g OGTTs in healthy undergraduates in Japan and investigated varying insulin and plasma glucose responses." (PMID 29629377, 2018). "Insulin therapy is currently among the best solutions available for the treatment of both types of diabetes (types 1 and 2)." (PMID 30510623, 2018). "In subcutaneous adipose tissue (SAT), higher stearoyl-CoA desaturase-1 (SCD1) expression has been related to improved insulin sensitivity in thiazolidinedione-treated type 2 diabetes mellitus patients." (PMID 30190473, 2018). "This would be very beneficial in diabetes treatment as it would result in a prolonged effect of insulin, and thereby improved glycemic control." (PMID 29558502, 2018). "Increased hepatic insulin clearance (HIC) is important in the pathophysiology of type 2 diabetes mellitus (T2DM)." (PMID 29791512, 2018). "In 30 patients with diabetes under insulin treatment, SG and SMBG values were measured for 2 weeks, and the correlation between the values was analyzed." (PMID 30100926, 2018). "Impaired insulin action in muscle results in insulin resistance and type 2 diabetes mellitus (T2DM)." (PMID 29710819, 2018). "Despite vanadium compounds having insulin-mimetic properties, and the first report on their therapeutic properties about diabetes and dyslipidemia appeared in the 20th century, its mode of action is still poorly understood at the molecular level." (PMID 30026756, 2018). "Type 2 diabetes mellitus and cancer are correlated with changes in insulin signaling, a pathway that is frequently upregulated in neoplastic tissue but impaired in tissues that are classically targeted by insulin in type 2 diabetes mellitus." (PMID 30208162, 2018). "Clinical outcomes in patients with diabetes mellitus who underwent percutaneous coronary intervention according to the treatment of insulin." (PMID 30532214, 2018). "Basal insulin analogues offer persons with type 2 diabetes mellitus (T2DM) adequate glycemic control combined with a favorable safety profile." (PMID 29460260, 2018). "Type 2 diabetes mellitus results from insulin resistance, a condition in which cells fail to use insulin properly, sometimes combined with an absolute insulin deficiency." (PMID 29324896, 2018). "The most compelling evidence for the role of ER stress in the development of T2DM comes from mutant INS-gene-induced diabetes of youth (MIDY), a syndrome characterized by genetic mutations in the insulin gene that cause it to misfold." (PMID 29770126, 2018). "His medical history included hypothyroidism due to Hashimoto’s disease, diagnosed at 62 years of age and treated with thyroid hormone replacement, as well as type 2 diabetes mellitus treated by self-injection of insulin with a good glycemic control." (PMID 29914537, 2018). "Diabetes and obesity are diseases of insulin and leptin resistance, in which the signaling responses to the hormones are attenuated." (PMID 29348454, 2018). "In the present study, HFD/STZ-induced diabetic ratsdisplayed elevated fasting blood glucose and HOMA-IR,accompanied by decreased serum insulin levels confirmingthe induction of diabetes in these animals." (PMID 29308616, 2018). "Sirtuins respond to environmental (diet and lifestyle) or metabolic (obesity, fasting, and diabetes) insults at mRNA and protein levels in insulin-sensing organs." (PMID 30574122, 2018). "It is well-known that the most important reason for the development of diabetes is that insulin resistance leads to impaired insulin secretion due to the impaired insulin signaling pathway, which leads to hyperglycemia." (PMID 30131712, 2018). "Diabetes mellitus is a group of metabolic diseases characterized by defects in insulin secretion, action or both." (PMID 30558349, 2018). "In a different context, the application of insulin for diabetes treatment and obesity are found to disturb spike rate of the sensory neuron, resulting in incorrect signaling for hunger." (PMID 30555289, 2018).
diabetes (continued). "Most respondents had poor knowledge in all the three knowledge categories, total knowledge of diabetes, general knowledge of diabetes and knowledge of insulin use." (PMID 30050608, 2018). "All these observations suggest that insulin-producing cells suitable for diabetes cell therapies can be produced from hESC/iPSC in vitro." (PMID 30594258, 2018). "An example is proinsulin mutations which lead to proinsulin misfolding, inducing β-cell ER stress and consequently permanent neonatal diabetes, also called mutant-insulin diabetes of the young (MIDY); its animal counterpart is the Akita mouse." (PMID 30412050, 2018). "BMI change after surgery was weakly correlated with duration of diabetes, HBA1c and insulin requirement; however, it had significant correlation with age (r = 0.405)." (PMID 29641734, 2018). "Established roles include degrading insulin and the amyloid beta peptide (Aβ), linking it to diabetes and Alzheimer’s disease." (PMID 29402917, 2018). "Experimental animal studies clearly demonstrate in which carnitine supplementation improves glucose tolerance during insulin- resistant states, such as diabetes or obesity." (PMID 29549241, 2018). "In Mexico, diabetes treatment is often an out of pocket expense and insulin treatment is perceived as costly." (PMID 30116737, 2018). "This is a first patient-reported dataset on hypoglycemia in Turkish, insulin-treated diabetes patients." (PMID 29433560, 2018). "In general, SSRIs can promote β-cell apoptosis, inhibit insulin secretion, and accelerate the transition of insulin resistance to dominant diabetes." (PMID 30126851, 2018). "Diabetes mellitus is a group of metabolic diseases characterised by hyperglycemia resulting from defects in insulin secretion, insulin action, or both." (PMID 30211323, 2018). "Diabetes mellitus (DM) is a chronic, metabolic disorder characterized by hyperglycaemia due to impaired glucose homeostasis, reduced insulin activity and insulin resistance." (PMID 30294283, 2018). "In fact, a study in rural Ghana found that spending on insulin for diabetes represented 60% of monthly income for individuals barely making minimum wage." (PMID 29879978, 2018). "There are theories of obesity [the “carbohydrate–insulin model”; (see, for example, Ludwig and Friedman, 2014; Goel, 2017)] as well as diabetes that rest on the insulin response to food." (PMID 29915545, 2018). "In the Czech Republic, more than 25% of insulin-treated patients visited a professional diabetes internet portal in the period between 2009 and 2013." (PMID 30404766, 2018). "Together with our cryoEM structures, our studies offer a road map to develop insulin-selective inhibitors or Aβ-selective enhancers to treat diabetes and Alzheimer's disease." (PMID 29596046, 2018). "Type 1 diabetes mellitus (T1DM) is a disease where destruction of the insulin producing pancreatic beta-cells leadsto increased blood sugar levels." (PMID 29845781, 2018). "This shift in metabolic homeostasis is common in states of metabolic dysfunction, where for instance in states of diabetes inhibition of insulin signaling shifts tissues toward fatty acid oxidation." (PMID 30061171, 2018). "Its content related to overly focusing on diabetes as a disease; the first ultrasound; how to handle glycemia and specifically hypoglycemic episodes; insulin dosages, and the estimated weight of the expectant child." (PMID 29720365, 2018). "Most diabetes guidelines recommend that the BI rate should be programmed in hourly intervals, according to the patient's circadian variation of insulin requirement and based on their individual fasting tests over a period of 6–10 h." (PMID 29974056, 2018). "At 16 weeks of age βEedKO animals exhibited marked glucose intolerance (top) and, intriguingly, by 25 weeks 100% of all knockouts exhibited overt diabetes (top), with reductions in both basal and glucose-stimulated insulin levels (bottom)." (PMID 29754954, 2018).